MIR5708 (microRNA 5708)
Synonyms: hsa-mir-5708
Gene: MicroRNA gene on chromosome 8 (80,241,389 to 80,241,473, forward strand). Ensembl gene ENSG00000265588.
Homologues: Orthologues: chimpanzee MIR5708 (100% identical).